ANXA1 (annexin A1)
Diseases named in the same sentence as ANXA1 in open-access papers (continued):
Sharing a sentence is not in itself a finding about the gene and the disease.
tumor (continued). "In the case of PyMT tumor cells, higher levels of Ltf, Spp1, Anxa1 and Cldn4 distinguish them from Neu and BRCA1-null tumor cells, and some of these genes have been associated with luminal progenitors." (PMID 32840210, 2020). "To characterize anxA1 expression in tumor vasculature, we assessed the binding characteristics of a large panel of antibodies to identify those that bind N-terminal–cleaved anxA1." (PMID 32497150, 2020). "In contrast to these models, the 4T1-Luc2, LLC-Luc2, and rat 13762 models were uniformly and consistently negative for vascular anxA1 expression, although each of these models exhibited anxA1 expression in tumor parenchymal cells to various degrees." (PMID 32497150, 2020). "We have previously reported TMA-studies indicating that cubilin (CUBN) and annexin A1 (ANXA1) expressed in the tumor cells are predictive markers in mRCC patients treated with sunitinib and sorafenib." (PMID 32321460, 2020). "We further identified rodent models of cancer that demonstrate anxA1 expression in tumor vasculature." (PMID 32497150, 2020). "Although reduction of ANXA1 in H1299 and A549 cells suppresses cell proliferation and invasion, in most cases, ANXA1 acts as a tumor suppressor inhibiting tumor growth." (PMID 33293474, 2020). "ANXA1 serves as a tumor suppressor expressing very little in the proliferating basal OS cells which is negatively regulated by the oncogene serine/arginine-rich splicing factor 3 (SRSF3)." (PMID 33291071, 2020). "Tumor microarray analysis further demonstrated positive vascular staining for anxA1 in 30 of 80 NSCLC samples, and positive staining of neoplastic cells was observed in 54 of 80 samples." (PMID 32497150, 2020). "In parallel, knockdown of ANXA1, thought to play a tumour-suppressive role in regulating exosomal release of tongue OSCC cell line HN5, led to reduced secretion of EVs in the exosome range and labelled exosome associated phosphorylated EGFT expression." (PMID 32054041, 2020). "Attempts to evaluate vascular anxA1 expression by immunohistochemistry are complicated by a lack of available antibodies that are both specific for anxA1 and bind the N-terminal–truncated form of anxA1 that has previously been identified in tumor vasculature." (PMID 32497150, 2020). "The defined time course of anxA1 expression in tumor vasculature in the B16-F10-Luc2 and Py230 models suggests a potential role for vascular anxA1 in facilitating or modulating growth in these tumors." (PMID 32497150, 2020). "Additional studies are required to determine the functional role of vascular anxA1 in these tumor models." (PMID 32497150, 2020). "Stromal-derived anxA1 has previously been shown to play a role in tumor angiogenesis, and anxA1 has been found to be induced in sprouting endothelial cells in an aortic ring assay." (PMID 32497150, 2020). "Strikingly, patients with ANXA1 positive tumours have, approximately, three times more probability of dying from BrC than those without expression." (PMID 33276477, 2020). "In general, ANXA1 is aberrantly expressed in both benign and malignant tumor stages compared with that in the healthy population." (PMID 32226026, 2020). "Previously, tumor uptake of anti-anxA1 antibody was observed in syngeneic rodent tumors generated by co-implantation of tumor spheroids with orthotopic tissue in a dorsal window chamber." (PMID 32497150, 2020). "In cancer cells, Annexin A1 expression levels are elevated, and F. nucleatum activates β-catenin through the FadA–E-cadherin–Annexin A1–β-catenin complex, thereby accelerating tumor progression." (PMID 33488528, 2020). "Annexin A1, which is also expressed by the tumour cells, acts as a modulator of the inflammatory process and has been linked to tumourigenesis." (PMID 30984541, 2019). "Other studies have also suggested a possible role for ANXA1 expression and tumour cell migration in pancreatic and prostate cancers." (PMID 30858446, 2019).
tumor (continued). "Our studies reveal annexin A1 mostly deriving from the cancerous tissue, whereas tumor-infiltrating leukocytes produce approximately one-third of this molecule in the TME." (PMID 31545917, 2019). "We further investigated annexin A1 concentrations using immunoblotting on an independent set of eight human-matched liver metastasis samples and observed its substantial abundance in tumor tissues." (PMID 31545917, 2019). "Intriguingly, a slight decrease in protein serum levels was observed, potentially suggestive of annexin A1 recruitment from the circulation to the tumor site, along with tumor progression." (PMID 31545917, 2019). "Collectively, these findings indicate that most of annexin A1 in the TME is produced by the tumor, whereas cells of the myeloid lineage, including neutrophils and T cells, also express this molecule in some measure." (PMID 31545917, 2019). "Our research studied for the first time the interaction of ANXA1 with the conditioned medium of endothelial cells, an attempt to simulate the tumour microenvironment." (PMID 30984541, 2019). "The anti‐inflammatory protein annexin A1 (ANXA1) has been reported to be associated with cancer progression and metastasis, suggesting that it plays a role in regulating tumour cell proliferation." (PMID 30984541, 2019). "In tumor metabolism, oxidative and reductive glutamine metabolism was found to be significantly impaired in HIF-1α/Anxa1-deficient cells, and associated with lower proliferation." (PMID 30213070, 2018). "In these particular forms of cancers, high expression of ANXA1 is positively correlated with disease severity and increasing tumour stage." (PMID 29614751, 2018). "In this study, tumour-derived EVs were initially purified from the supernatant of both WT and ANXA1 KO MIA PaCa-2 cells." (PMID 30518142, 2018). "The novelty we highlighted is based on the contribution of ANXA1 in PC EVs biogenesis as a further mechanism by which the protein can influence the tumour cell behaviour." (PMID 30518142, 2018). "This outcome highlights the effect of the loop ANXA1/EVs not only on tumour cells but also on PC surrounding tissues as indicated by the formation of the capillary-like structures from endothelial cells." (PMID 30518142, 2018). "The oncogenic functionality of this miRNA is mediated via its potential to target annexin A1 mRNA, a tumor suppressor gene involved in inhibition of the NF-κB pathway." (PMID 29705927, 2018). "Generally, some aspects as tumour microenvironment, immunity, and metastatization will be explored in in vivo models in order to better define the impact of ANXA1 on EVs biogenesis and of the complex ANXA1/EVs in PC progression." (PMID 30518142, 2018). "The mRNA level of ANXA1 (P<0.0001) was extremely and significantly lower in tumor tissues than in the corresponding tumor-adjacent tissues." (PMID 29416786, 2018). "The activation of endothelial cells by EVs obtained from WT MIA PaCa-2 cells not only indicated their impact on tumour progression but also confirmed the role of ANXA1 in this process." (PMID 30518142, 2018). "The oncogenic functionality of this miRNA is mediated via its potential to target the annexin A1 mRNA, which is reported as a tumor suppressor." (PMID 29705927, 2018). "A similar phenotype was seen in nasopharyngeal cancers in which primary tumours had lower ANXA1 expression when compared to lymph node metastasised tumours." (PMID 29614751, 2018). "To test the protein impact on the tumour aggressiveness, we analyzed the behaviour of wild type (WT) and/or ANXA1 KO MIA PaCa-2 cells, treated with EVs-depleted and EVs-associated, enriched in exosomes, fractions from recipient cells." (PMID 30518142, 2018). "The effects of ANXA1 on tumour aggressiveness were investigated by Wound-Healing and invasion assays and microscopic analysis of the Epithelial to Mesenchymal Transition (EMT)." (PMID 30518142, 2018).
tumor (continued). "Like the miRNA-196-based regulatory mechanism discussed in relation to ANXA1 release, miRNA-129-2, a tumor suppressor in glioma and hepatocellular carcinoma, directly targets HMGB1 and inhibits its release." (PMID 29666625, 2018). "In the current study, we evaluated the effects of ANXA1 signalling on macrophage polarization in the tumour microenvironment." (PMID 29263330, 2017). "At 5 weeks post injection, tumour growth was significantly higher in the ANXA1+/+ group compared to ANX1−/− group." (PMID 29263330, 2017). "Increased expression of annexin A1 has been shown to be correlated with KRAS mutation, suggesting that annexin A1 is specifically involved in KRAS mutation-mediated tumor development or metastasis in CRC." (PMID 28423508, 2017). "Concomitantly, ANXA1 mRNA levels were significantly reduced in the tumor samples compared to paired normal epithelia." (PMID 28754915, 2017). "We next explored potential signalling pathways to identify the mechanism by which ANXA1 enhances tumour cell migration." (PMID 29263330, 2017). "With its contributions prominent in a wide array of cellular functions, ANXA1 either functions as a pro-cancerous or tumor-suppressive protein depending on the contextual tumor tissue/cell type." (PMID 29233185, 2017). "Tumor specimens with up-regulated miR-196a2 and down-regulated annexin A1 showed high pathological grade, larger tumor size, and advanced stage." (PMID 29091952, 2017). "In several malignancies associated with liver, pancreas, lung, prostate and brain, high ANXA1 expression has been correlated with tumor progression, aggressiveness and even metastasis." (PMID 29233185, 2017). "After filtering for missing values, a total of 20 out of 235 tumor tissues displayed ANXA1 positivity." (PMID 26657294, 2016). "We hereby report that ANXA1 and CALD1 proteins are independent markers for tamoxifen therapy outcome and are associated to fast tumor progression." (PMID 26657294, 2016). "Refinements to the candidate list were made by adding peptides representing the proteins IGJ and ANXA1, because these peptides were the only candidates even trend upregulated in the EC tumour group (P≤0.25)." (PMID 27350604, 2016). "Forest plot analysis demonstrated that tumours expressing low levels of the metagene derived from ANXA1 (dichotomised at the median) showed a benefit from trastuzumab (multivariate: hazard ratio [HR] = 0.16 [95% CI 0.05–0.5] p = 0.002; fdr = 0.03)." (PMID 26358523, 2015). "Our Annexin A1 depletion in TNBC cell lines further suggests its tumorigenic role by promoting tumor cell migration through increased mTOR signaling." (PMID 26000884, 2015). "Given the potential role for ANXA1 in multiple neoplasms such as the regulation of cell proliferation, differentiation and metastasis, we focused on the molecular mechanisms by which ANXA1 modulates these cellular responses." (PMID 25490767, 2014). "In the present study, we provided preliminary evidence that ANXA1 expression seems to be tumor type-specific in these malignant tissues." (PMID 25038797, 2014). "The role of ANXA1 in tumours is paradoxical since ANXA1 appears to behave either as a tumour suppressor or an oncogenic gene." (PMID 25510623, 2014). "The mast cells and neutrophils in the peritumoral and tumor sections revealed high expression of ANXA1/FPR2." (PMID 25490767, 2014). "Our data confirmed that ANXA1 expression is different in different types of tumor and plays a multifaceted role in cancer development and progression." (PMID 25038797, 2014). "The epithelial cells of control, peritumoral and tumor laryngeal tissues displayed immunoreactivity to ANXA1 and FPR2/ALX, as well as co-localizations of the proteins, in the plasma membrane, cytoplasm and nucleus." (PMID 25490767, 2014). "The anti-inflammatory protein annexin A1 (ANXA1) has been associated with cancer progression and metastasis, suggesting its role in regulating tumor cell proliferation." (PMID 25490767, 2014).
tumor (continued). "In the peritumoral and tumor samples, we observed a marked reduction of ANXA1 and FPR2/ALX protein expression compared with the corresponding control tissues." (PMID 25490767, 2014). "Accumulated evidences have indicated that ANXA1 deregulation and sub-cellular localization are involved in the development, invasion, metastasis and drug resistance of a variety of cancers suggesting a tissue type-specific role for ANXA1 in tumour advancing." (PMID 25510623, 2014). "ANXA1 protein was detected in 81 % (97/120) of tumours, CAV-1 in 44 % (54/122) of tumours and EphA2 in 74 % (90/121) of tumours." (PMID 25594008, 2014). "ANXA1 appearance is in a tissue- and tumour-specific manner and its anomalous expression is closely related to cancer progression." (PMID 25510623, 2014). "Collectively, our results provide the systematic survey of ANXA1 for various benign human tissues and tumor specimens." (PMID 25038797, 2014). "Specifically, immunohistochemistry for ANXA1 in liver metastases displayed a significant reduction of this protein in tumor cells." (PMID 25038797, 2014). "Thirty one % (35/113) of tumours tested expressed all three markers and 19 % (21/112) had moderate or strong expression of ANXA1, CAV-1 and EphA2." (PMID 25594008, 2014). "Increased Annexin A1 expression is reported to correlate with anti-cancer drug resistance in some tumor cells in vitro." (PMID 23786757, 2013). "The proportion of patients with low Annexin A1 expression was significantly higher amongst those with moderate/poorly differentiated tumor (78/167) compared to those with well differentiated tumor (18/65)." (PMID 23786757, 2013). "Patients with moderate/poorly differentiated tumor and low Annexin A1 expression benefited from TPF induction chemotherapy as measured by distant metastasis-free survival (P=0.048, HR=0.373) as well as overall survival (P=0.078, HR=0.410)." (PMID 23786757, 2013). "This anti-tumor effect was overcome, however, in mice immunized with annexin A1-expressing apoptotic S2-mOVA cells." (PMID 23638088, 2013). "The proportion of patients with low Annexin A1 expression was higher amongst the patients with moderate/poorly differentiated tumor than those with well differentiated tumor." (PMID 23786757, 2013). "Similar to the pattern we observed for Anxa1 expression, we found that FoxM1 mRNA was also up-regulated in tumor cells than the paired adjacent normal brain tissues." (PMID 23991102, 2013). "Annexin A1 index was estimated as the proportion of tumor cells (low and high, <50% and ≥50% of stained cells, respectively) to Annexin A1 cellular membrane and cytoplasm staining." (PMID 23786757, 2013). "Accordingly, Anxa1 knockout mice present defects in tumor growth, metastasis, angiogenesis and wound healing suggesting the importance of Anxa1 in regulating tumor progression." (PMID 23991102, 2013). "Tumor growth and metastasis were significantly decreased when tumors grew in host animals unable to express annexin A1." (PMID 23077482, 2012). "The challenges for future investigation are to identify the role of Annexin A1 in chemotherapies or ionizing irradiation induced potent anti-tumor cell vaccine." (PMID 23251389, 2012). "We combined the lists of molecules from the processes or functions that involve various components in tumor stroma to generate the list of molecules that comprises the tumor stroma interactome which interacts with annexin A1." (PMID 23077482, 2012). "From the raw data obtained previously using mouse whole genome microarrays to run tumor samples from annexin A1 knockout and wildtype mice, this study performed thorough systems analysis." (PMID 23077482, 2012). "This revealed annexin A1 to be an effective regulator in tumor stroma and suggested a mechanism that annexin A1 affects tumor development and metastasis through interaction with the various components in the microenvironment surrounding the tumor cells." (PMID 23077482, 2012).
tumor (continued). "Here, we used systems biology approach to analyze the tumors in whole animal models on the background of absence or presence of annexin A1 to show the global effects of annexin A1 on tumor stroma." (PMID 23077482, 2012). "Among the immune cells that were present in tumor stroma, T cell related processes stood out, which is consistent with the recently identified effects of annexin A1 on T cell functions." (PMID 23077482, 2012). "We have previously showed the impaired tumor growth, metastasis, angiogenesis and wound healing in annexin A1 knockout mice." (PMID 23077482, 2012). "Using AnxA1- knock out (KO) mice, it has been determined that tumour growth and metastasis are significantly decreased, whereas rodent survival and tumour necrosis are significantly increased when tumours grow in AnxA1-KO mice." (PMID 23116199, 2012). "The function of annexin A1 apparently follows a biphasic mode during tumorigenesis, where it functions as a tumor suppressor during the early stages of the disease and as a potent stimulator of tumor progression in a late stage disease." (PMID 22929401, 2012). "This showed a mechanism that annexin A1 affects tumor development and metastasis through interaction with the various components in the microenvironment surrounding the tumor cells." (PMID 23077482, 2012). "Annexin A1 is a multi functional molecule which is involved in inflammation, innate and adaptive immune systems, tumor progression and metastasis." (PMID 23077482, 2012). "MMP13 was shown to promote angiogenesis, which is consistent with the finding in this study of down-regulated MMP13 expression and impaired tumor growth and angiogenesis in tumors on annexin A1 knockout mice." (PMID 23077482, 2012). "We recently showed the pro-angiogenic functions in tumor development for annexin A1 which was previously known as an inflammatory protein." (PMID 23077482, 2012). "ANXA1 expression in prostate carcinogenesis correlates with enhancing tumor aggressiveness through increasing IL-6 expression and activity." (PMID 20927350, 2010). "Reduced ANXA1 expression has been observed in many different human malignancies, and the overexpression of ANXA1 in tumor cells leads to growth suppression and/or apoptosis." (PMID 21060779, 2010). "Furthermore, we observed an upregulation of ANXA1, which has been shown to modulate inflammatory properties by promoting macrophage differentiation to its protumoral M2 phenotype, promoting tumour progression." (PMID 41362277, 2026). "Conversely, overexpression of ANXA1 slightly exacerbated tumor growth." (PMID 40484878, 2025). "The main DAMPs include ATP, calreticulin (CRT), high mobility group box protein B1 (HMGB1), heat shock protein (HSP), type I interferon (IFN I) and Annexin 1 (ANXA1), which then activate and recruit APCs such as macrophages and DCs to activate T cells reactive to tumor antigens." (PMID 41246345, 2025). "In addition, TCGA HNSCC bulk RNA-seq data confirmed the downregulation of ANXA1 in tumor samples, and its expression was again positively correlated with the senescence program score." (PMID 39896470, 2025). "So, we observed different roles of LL-37 and ANXA1 that are not entirely in accordance with the conventional function of FPRs as their receptors, which is generally associated with the promotion of tumor progression in terms of cell motility and resistance." (PMID 40227604, 2025). "The ANXA1 protein is expressed on tumor cells and TAMs at the tissue level." (PMID 40361334, 2025). "Compared with the control group, only ANXA1 knockdown inhibited tumor growth." (PMID 40390008, 2025). "Notably, PD-1 blockade further augmented the infiltration of CD8+ T cells and CD11c+ DCs, suggesting that anti-PD-1 treatment and ANXA1 knockdown synergistically promote the anti-tumor immune response." (PMID 40484878, 2025). "However, ANXA1 exhibits both tumor-promoting and tumor-suppressing properties, depending on the cancer type and stage." (PMID 41283264, 2025).